CRP (C-reactive protein)
Diseases named in the same sentence as CRP in open-access papers (continued):
Sharing a sentence is not in itself a finding about the gene and the disease.
depression (continued). "Patients with low levels of CRP (<1 mg/L) showed improvement on the Montegomery-Åsperg Depression Rating Scale (MADRS), with scores three points higher after escitalopram treatment, compared with nortriptyline." (PMID 25856677, 2015). "Increased levels of the inflammatory markers such as C-reactive protein (CRP), haptoglobin, IL-6, and TNF-α have been reported to be associated with depression." (PMID 25705518, 2015). "The linear model regressed on the CRP levels, anxiety scores, depression scores, and daily step counts at one month after stroke explained 21% of the variance in FAS scores at six months and 24% variance at 12 months." (PMID 26599129, 2015). "Cross-sectional associations between C-reactive protein (CRP) levels and fatigue scores, controlling for anxiety, depression and daily step counts (n = 65)." (PMID 26599129, 2015). "Relationships between CRP levels at one month and fatigue scores at 6 and 12 months, controlling for anxiety, depression, and daily step counts (n = 65)." (PMID 26599129, 2015). "Of the inflammatory markers studied in the present study, CRP, IL–6 and TNF- α have been previously shown to have an association with depression / anxiety." (PMID 26445118, 2015). "We tried to address this in part, by controlling for the inflammatory biomarkers CRP and IL6 in the multivariable analysis and our results suggest that plasma levels of sVCAM-1 was independently associated with depression symptoms." (PMID 26040277, 2015). "There are also evidences from large-study that low-grade chronic inflammatory markers, such as C-reactive protein and interleukin-6 are connected with cognitive symptoms of depression." (PMID 25793613, 2015). "For incident storage LUTS, removing CRP from the final model produced a moderate decrease in the multi-adjusted effect size of depression (Model 1: 1.26 (1.01, 4.02) to Model 2: 1.18 (0.96, 3.4) and model fit (R2change: 0.253–0.221)." (PMID 26445118, 2015). "In favor of this theory, many recent clinical data have shown elevated concentrations of inflammatory markers (including TNF-α, IL-6, IL1-β, and CRP) in the blood and in the cerebral spinal fluid of patient with major depression." (PMID 25386150, 2014). "Sleep disturbances in patients with RA occur due to multifactorial origins and multidirectional disease-related variables like the disease activity, depression, pain, fatigue, functional disability, radiographic score, quality of life and the CRP levels." (PMID 24400031, 2014). "Further work is needed in order to understand the processes through which depression and CRP interact to affect cardiac recovery." (PMID 24239712, 2014). "These authors reported that elevated depression symptoms predicted a lesser decrease in CRP across the month following the cardiac event, which the authors describe as reflecting a poorer remission in the underlying inflammatory process." (PMID 24239712, 2014). "A few population-based studies have investigated the relationship between C-reactive protein (CRP) and de novo depression." (PMID 25329298, 2014). "The longitudinal design of the ARCS study allows for the temporal relationship between depression, CRP and length of stay to be analysed." (PMID 24239712, 2014). "Further work is needed to explore the exact physiological pathways through which depression and CRP interact to affect recovery in CABG patients." (PMID 24239712, 2014). "These authors studied 232 patients undergoing CABG surgery and found that higher pre-operative high sensitivity (hs)-CRP was predictive of depression symptoms up to six months following surgery, after controlling for covariates." (PMID 24239712, 2014). "In particular, SLI in basal ganglia and vascular risk factors including higher BMI levels, and inflammation markers, CRP, TNF-α, hs-CRP, and IL-6 can increase the risk for depression." (PMID 24752391, 2014).
depression (continued). "We were able to show that patients with elevated depression symptoms on the BDI were at increased odds of an extended hospital stay, and that this association was partially mediated by a greater change in CRP from baseline values to 4–8 days post-surgery." (PMID 24239712, 2014). "Chronic inflammation has been suggested as an important mechanism related to depression, such as: C-reactive protein (CRP), interleukin-6 (IL-6), IL-1, IL-18." (PMID 25061971, 2014). "In this study we aimed to examine the role of CRP in the relationship between pre-operative depression and length of post-operative hospital stay in patients undergoing elective CABG surgery." (PMID 24239712, 2014). "Lastly, in subjects with a lifetime history of depression, IL-6 and CRP serum levels were found to be elevated, where IL-6 methylation in WBC DNA showed an inverse correlation with circulating IL-6 and CRP." (PMID 23977113, 2013). "This study demonstrated that depressed patients with higher levels of the inflammatory markers TNF-α and CRP showed a decrease in depression rating scores over the course of the study." (PMID 24385966, 2013). "Levels of IL-6 and CRP have been shown to be elevated in individuals with depression and decreased after antidepressant treatment." (PMID 23676005, 2013). "Both depression score (standardized β = 0.35, P < 0.001) and CRP level (standardized β = 0.35, P < 0.001) were significantly associated with pain, even after adjusting for clinical covariates in the regression analysis." (PMID 22156289, 2012). "In this context, there is abundant evidence that clinical depression is an immuno-inflammatory disorder characterized by among other things increased levels of PICs and acute phase proteins, including C-reactive protein and haptoglobin." (PMID 22747645, 2012). "In logistic analysis, the combined effects on the risk of severe pain (pain score in the highest tertile) increased linearly with depression score and CRP level." (PMID 22156289, 2012). "Genetic studies have the potential to shed light on the role of CRP in the relationship between depression and anxiety and the metabolic syndrome, since genes influencing CRP levels will not be influenced by these potential confounding factors." (PMID 21296145, 2011). "The current study provides novel evidence for a depression-by-CRP gene interaction effect on the metabolic syndrome." (PMID 21296145, 2011). "C-reactive protein levels, physical pain, symptoms of arthritis and depression decreased significantly during the past 12 months of treatment with quetiapine, while treatment with selective serotonin reuptake inhibitors and mirtazapine remained the same." (PMID 20157432, 2010). "This case report is supports the suggestion that joint inflammatory pathways between arthritis and depression as symptoms of arthritis, pain and depression are simultaneously lifted when CRP levels are lowered." (PMID 20157432, 2010). "Secondly, the combination of selective serotonin reuptake inhibitors (SSRI), antidepressants and quetiapine as atypical antipsychotic treatment lifted the patient's depression, physical symptoms and CRP levels." (PMID 20157432, 2010). "Inflammatory markers such as C-reactive protein (CRP) and interleukin-6 are associated with depression, and inflammatory processes have been suggested to be an important link between psychosocial stress and cardiovascular diseases such as atherosclerosis." (PMID 19888340, 2009). "Women who reported that they suffered from an ongoing depression (n = 26) displayed significantly higher levels of CRP than women denying being depressed (n = 155): 1.69 ± 1.44 versus 1.14 ± 1.17 mg/L (p < 0.05)." (PMID 18384670, 2008). "The correlations between the personality traits and CRP were observed also after exclusion of subjects reporting ongoing depression (n = 26)." (PMID 18384670, 2008). "In line with this notion, women in our study reporting ongoing depression displayed elevated CRP levels." (PMID 18384670, 2008).
depression (continued). "Exploring the possible relationship between personality and CRP is motivated also by the fact that not only depression and panic disorder, but also certain personality traits, have been suggested to enhance the risk for cardiovascular disease." (PMID 18384670, 2008). "Since previous studies have shown that depression is often associated with high harm avoidance and low self-directedness state, it might be suggested that the observed association between these personality traits and CRP merely reflects an underlying depression." (PMID 18384670, 2008). "For example, a recent study compared C-reactive protein levels in cardiac patients with major depression before and after treatment with selective serotonin reuptake inhibitors (SSRIs)." (PMID 17397549, 2007). "CRP has attracted more attention over the last years, as multiple associations with cardiovascular diseases, COPD, osteoporosis and even depression were identified." (PMID 16670014, 2006). "In multivariate analyses, not receiving surgical resection and higher C-reactive protein (CRP) levels were independently associated with depression in the overall CCA cohort and in the ICC subgroup." (PMID 41618318, 2026). "Future studies could further explore the clinical applications of biomarkers in CVD and depression by developing and validating biomarkers that can predict or diagnose CVD and depression (such as CRP and leptin)." (PMID 41601490, 2026). "However, in the analysis with multivariate generalized estimating equations, only log‐transformed CRP and NLR remained significantly associated with depression." (PMID 40851223, 2026). "Elevated CRP levels are consistently observed in patients with anxiety and depression." (PMID 41048872, 2025). "While each of these biological mechanisms may play a significant role in the nexus between physical activity and depression, this paper focuses on inflammation, and more specifically, the inflammatory marker, C-reactive protein (CRP)." (PMID 41661985, 2025). "Mental health practitioners could incorporate inflammatory marker panels (e.g., IL-6, TNF-α, CRP) into assessment protocols, particularly for patients with depression subtypes characterized by elevated inflammation." (PMID 40964429, 2025). "A meta-analysis of 107 studies in the general adult population found that individuals with depression had elevated C-reactive protein (CRP), interleukin (IL)-3, IL-6, IL-12, IL-18, soluble interleukin 2 receptor (sIL-2R), and tumor necrosis factor alpha (TNF-α) levels with medium-effect sizes." (PMID 39902492, 2025). "Conversely, a weaker positive link was found between CRP levels and CES-D scores, implying that higher CRP levels may be associated with higher depression scores." (PMID 41661985, 2025). "Anti-inflammatory treatments could reduce inflammation-related depression in those with high circulating levels of cytokines, but this was unlikely to be the case in the current study given the relatively low levels of CRP observed here." (PMID 41374012, 2025). "The purpose of this study was to explore a potential connection between Chlamydia and depression, and whether C-reactive protein (CRP) modifies this effect." (PMID 41153310, 2025). "Using cross-sectional data collected when participants were aged 18 years, the aim of this study is to apply a mediation model to assess if CRP directly mediates any relationship between pain-type somatic symptoms and anxiety and/or depression during late adolescence." (PMID 40823322, 2025). "It is not clear why CRP-depression associations are less consistent in psoriasis than in the general population." (PMID 39959848, 2025). "Consistent with these theories, a recent prospective study and meta-analysis of longitudinal studies on the bidirectional connections between inflammation and depression revealed consistent evidence that increased CRP and fibrinogen predict future MDD symptoms." (PMID 40686933, 2025).
depression (continued). "Moreover, depression symptom severity, as well as specific symptoms including cognitive symptoms, interest activity, and suicidality correlated with CRP levels only among females." (PMID 40305313, 2025). "Individuals with elevated CRP levels are more likely to experience treatment-resistant depression, indicating that inflammation may play a role in the efficacy of antidepressant therapies." (PMID 40004109, 2025). "This study analyzed data from 180 patients with ALS to develop and validate a nomogram for predicting depression risk using six variables: completion of 9 years of compulsory education, sleep disorders, anxiety, ALSFRS-R total scores, CRP levels, and SIRI values." (PMID 41018179, 2025). "Using a similar paradigm, another study is assessing the impact of carbidopa/levodopa, the anti-Parkinsonian dopamine pro-drug, on resting state functional connectivity in classic reward circuitry and anhedonic depression using a CRP cut-off to enrich the patient cohort." (PMID 40002494, 2025). "Inflammatory markers, such as C-reactive protein (CRP), are elevated in subgroups of patients with depression with enhanced neurovegetative symptoms (e.g., weight gain and increased hunger) and are linked to genetic risk factors, according to clinical investigations." (PMID 40002422, 2025). "Our study showed that in terms of predictive performance, the area under the ROC curve of AGP for depression was 0.70, which was much larger than the area under the ROC curve of other inflammatory markers such as CRP (0.58) and HDL-related inflammation indexes (0.65)." (PMID 40530060, 2025). "A notable strength of this study lies in its large sample size and examination of how the network structure of anxiety–depression symptoms and CRP levels differs across different insomnia severity levels, offering valuable insights into the underlying psychosomatic mechanisms." (PMID 41048872, 2025). "Moreover, the relationship between genetic factors and inflammation is also supported by research examining the role of C-reactive protein (CRP) and interleukin-6 (IL-6) in depression." (PMID 40004109, 2025). "This suggests that while both depression and CRP are cardiovascular risk factors, CRP does not function as a primary mediator in this pathway." (PMID 40904459, 2025). "Notably, a priori inflammation-stratified designs and secondary analyses suggest that baseline CRP and related markers moderate antidepressant response to n-3 PUFAs, consistent with a “inflamed depression” subtype more likely to benefit." (PMID 41228497, 2025). "On the one hand, sleep disorders could lead to an increase in inflammation, and the elevated levels of inflammatory markers CRP and IL-6 could increase the prevalence of depression symptoms." (PMID 40688961, 2025). "Most studies, including our initial findings, confirm elevated CRP and IL-6 levels in depression." (PMID 40428308, 2025). "The CRP plays a role in regulating and amplifying the inflammatory process and is involved in neuroinflammation, which may be a mechanism for depression in patients with ALS." (PMID 41018179, 2025). "Notably, CRP demonstrated the lowest predictability, indicating that its variability is primarily explained by factors external to the anxiety–depression symptom network." (PMID 41048872, 2025). "Elevated serum CRP levels have also been significantly associated with mood disorders such as depression and bipolar disorder, suggesting a negative impact of active inflammation on patients’ overall well-being." (PMID 40806940, 2025). "The potential mechanism of the relationship between grip strength and depression trajectory may be mediated by the influence of specific brain area volume, C-reactive protein, neutrophils, and white blood cells." (PMID 40017457, 2025). "However, few studies have measured serum inflammatory markers of depression in psoriasis and most of them have examined CRP." (PMID 39959848, 2025).
depression (continued). "This therapeutic benefit occurred independently of changes in CRP levels.At present, large-scale prospective trials are still needed to validate the efficacy of infliximab in populations with cancer and comorbid depression." (PMID 41000397, 2025). "Baron and Kenny's (1986) mediation framework was used to explore whether CRP acts as a mediator between depression and anxiety scores, and pain-type somatic symptoms." (PMID 40823322, 2025). "This evidence supports the idea that cancer patients experiencing fatigue, anxiety, and depression may have elevated levels of circulating inflammation markers, such as interleukin‐6 (IL‐6) and C‐reactive protein (CRP)." (PMID 40387308, 2025). "Moreover, depression scores were weakly positivelyassociated with CRP levels, BMI-z score, WC and WHtR." (PMID 40110388, 2025). "There is some evidence that greater adiposity may be related to higher levels of CRP, poorer mobility outcomes, symptoms such as greater depression and pain, as well as worse cardiorespiratory fitness." (PMID 40290097, 2025). "Patients with depression typically exhibit elevated levels of inflammatory markers, such as C-reactive protein (CRP), tumor necrosis factor-α (TNF-α), and interleukin-6 (IL-6), which can impact the functioning of the central nervous system, causing mood disorders and cognitive decline." (PMID 40313907, 2025). "This in turn leads to beneficial effects, including reduced LDL cholesterol and insulin resistance (HOMA‐IR), increased brain‐derived neurotrophic factor (BDNF) levels, and decreased depression and anxiety, as well as decreased markers of inflammation (CRP, and calprotectin) and cancer (CEA)." (PMID 41142011, 2025). "However, additional studies revealed that malignant tumor patients with depression exhibited increased inflammatory cytokines such as CRP, which enhance immunity, particularly in gastrointestinal cancer patients." (PMID 41446305, 2025). "The prevalence of chronic systemic inflammation in depression was estimated by another biomarker in a study conducted in the United Kingdom, a quarter of patients with depression show evidence of chronic systemic inflammation (CRP > 3 mg/L)." (PMID 40060385, 2025). "However, the cross-sectional single-point measurement of CRP is not an appropriate index to evaluate the continuous impact of elevated CRP on depression and CVD." (PMID 41179571, 2025). "In addition, higher CRP levels have been found in the peripheral blood and cerebrospinal fluid of patients with a depression compared with healthy individuals." (PMID 39504461, 2025). "Since the CRP has been demonstrated it had a great predictive effect on depression." (PMID 40530060, 2025). "Very small but consistent bivariate correlations were observed between well‐being, stressful life events, CRP, and physical activity across groups, aligning with a UK Biobank study that examined other psychosocial variables (e.g., depression, loneliness) in back pain." (PMID 40685555, 2025). "Unlike the widely studied proinflammatory cytokines (IL-6, TNF-α, and CRP), these markers are rarely investigated in psychiatric research, despite their potential as indicators of both the metabolic and inflammatory background of depression." (PMID 40507778, 2025). "Further research supports wider sex-specific CRP-depression links for women, which may be genetic- or hormone-driven, although findings are not unanimous." (PMID 39959848, 2025). "While CRP and BDNF are more accessible for extraction and detection, CRP reflects generalized systemic inflammatory without specificity for depression, and BDNF, although associated with neuroplasticity, lacks specificity across psychiatric disorders." (PMID 41425661, 2025). "Interestingly, CRP levels and the response to dopaminergic therapies in individuals with depression were reported to be related, a finding that indicates that these are complex pathways deserving more research to build on." (PMID 40565981, 2025).